HIF1A (hypoxia inducible factor 1 subunit alpha)
Diseases named in the same sentence as HIF1A in open-access papers (continued):
Sharing a sentence is not in itself a finding about the gene and the disease.
leukemia (continued). "In conclusion, we have identified a compound that as a single agent selectively kills a subgroup of MLL-r and CALM-AF10 leukemia cells characterized by relatively low-expression levels of HIF1α and MEIS1." (PMID 30670779, 2019). "Based on previous findings, IDA, or IDA in combination with triptolide, also suppresses the expression of HIF-1α and related downstream target genes in leukemia stem cells." (PMID 28423608, 2017). "As a consequence, inhibiting HIF-1α impaired leukemia cell migration, chemotaxis, invasion and transendothelial migration in vitro, and this resulted in impaired bone marrow homing and leukemia progression in vivo." (PMID 27447550, 2016). "We have previously reported that in acute promyelocytic leukemia (APL, AML-M3) HIF-1α inhibition delays leukemia progression and synergizes with retinoic acid in eradicating LICs." (PMID 27447550, 2016). "The role of HIF-1α in leukemia, and in particular in acute myeloid leukemia, is only recently beginning to be characterized and at the present time it is highly debated." (PMID 27447550, 2016). "Taken together, our results support further clinical studies of emetine as an anti-leukemia novel drug in combinatory therapies and highlight the importance of HIF-1α, emetine molecular target, in drug resistance." (PMID 26992240, 2016). "By using an inhibitor of HIF-1α, it was suggested that HIF-1α is a key regulator of leukemia stem cell maintenance in AML." (PMID 27447550, 2016). "In this study, we find that HIF-1α promotes leukemia progression in the acute monocytic leukemia sub-type of AML through activation of an invasive phenotype." (PMID 27447550, 2016). "With this cell line, we repeated the cell proliferation assay and our data showed that the growth inhibitory effect of leukemia cells by prolyl hydroxylase inhibitors is HIF-1α independent." (PMID 27764789, 2016). "In acute myeloid leukemia, HIF-1α has been found overexpressed in a sub-group of cancer cells with leukemia propagating capacity and was shown to regulate leukemia stem cell maintenance." (PMID 24711541, 2014). "As a consequence, inhibition of HIF-1α blunts leukemia progression, and also exquisitely cooperates with retinoic acid in eradicating leukemia-initiating cells." (PMID 24711541, 2014). "Strikingly, while short ATRA treatment or HIF-1α silencing only modestly affected the survival of transplanted animals, combined treatment exquisitely synergized in preventing leukemia engraftment." (PMID 24711541, 2014). "On the other hand, our work places HIF factors as important regulators of the pathogenesis and response to therapy of acute promyelocytic leukemia, and prompt further investigation into the role of HIF-1α factors in other types of leukemia." (PMID 24711541, 2014). "We have previously found that, in the M3 subtype of AML, HIF-1α is activated by the fusion protein PML-RARα throughout the leukemia bulk, where it regulates not only self-renewal of leukemia stem cells but also cell migration, chemotaxis and neo-angiogenesis." (PMID 25452766, 2014). "Herein we supply evidence for a significant antiproliferative effect of the nutritional supplement CellfoodTM on leukemia cell lines by inducing cell death through an apoptotic mechanism and by altering cell metabolism through HIF-1α and GLUT-1 regulation." (PMID 24016597, 2013). "We supplied evidence for an antiproliferative effect of CF on leukemia cell lines by inducing cell death through an apoptotic mechanism and by altering cancer cell metabolism through HIF-1α and GLUT-1 regulation." (PMID 24016597, 2013). "We have observed that not only leukemic cells but also the surrounding stroma expresses HIF-1α, implying that hypoxia is an intrinsic property of the leukemia microenvironment." (PMID 21853076, 2011). "Targeting HIF-1α and P-gp appears promising for anti-leukemia strategies." (PMID 41394810, 2025).
leukemia (continued). "Hypoxia-inducible factor-1α (HIF-1α), a pivotal regulator, emerges as a potential therapeutic target by orchestrating immunometabolic homeostasis, suppressing fibrosis, preserving gut microbiota balance, and retaining graft-versus-leukemia (GVL) effects." (PMID 40791591, 2025). "Inhibition of HIF1-α may therefore represent a viable strategy for interfering with disease progression and inducing chemosensitivity in leukemia." (PMID 39994019, 2025). "The HME of leukemia up-regulates HIF-1α and stimulates CLL cell survival and proliferation." (PMID 37588219, 2024). "Although the research on HIF-1α inhibitors in leukemia is at an early stage, based on the deepening research and the functional analysis of hypoxia-inducible factor in leukemia in the existing literature, HIF-1α inhibitors are expected to be a reliable treatment option for leukemia patients." (PMID 35684364, 2022). "Interestingly, increased HIF1A has been shown to mediate cancer stem cell maintenance in leukemia, a highly proliferative cell type." (PMID 34580712, 2022). "Importantly, for this work it has been shown that HIF-1α is overexpressed in various types of leukemia, including pediatric ALL and interestingly the high expression of this transcription factor correlates with poor survival." (PMID 35163649, 2022). "They observed that HIF-1α promoted the arrest of leukemia cells in the intraosseous niche, and speculated that this might contribute to the persistence of residual leukemic cells in AML." (PMID 36231060, 2022). "Besides increased basal expression of HIF factors compared to normal cells across different leukemias expression of HIF1α within the CLL and ALL leukemic compartment increases upon co-culture of leukemic blasts with BM stromal cells." (PMID 36059690, 2022). "In addition, inducible HIF1α deletion in the MLL-AF9 model resulted in increased recovery upon withdrawal of chemotherapeutic regimens, thus suggesting that HIF1α inhibition cannot be expected to improve chemotherapy sensitivity in all leukemia." (PMID 36059690, 2022). "This study revealed that HIF1α acts as a master regulator in the pathogenesis of leukemia and might be used, as a therapeutic target for CML." (PMID 35847841, 2022). "Also, pharmacologic inhibition of HIF1α in AML cells carrying the AML1-ETO or PML-RARα oncoproteins suppressed leukemia expansion in vivo." (PMID 36059690, 2022). "In addition, echinomycin decreased MYC and HIF1α protein levels in leukemia cell line THP1 from hematologic malignancies as well." (PMID 33572152, 2021). "In MLL-rearranged leukaemia, increased glycolytic activity in combination with increased levels of HIF-1α leads to resistance to inhibition of mitochondrial respiration, whereas inhibitors against HIF-1α are currently in development and have been proven to have antitumour activity in MM." (PMID 34968247, 2021). "There were some data showed that HIF1A over-expressed in some leukemia cells." (PMID 33109189, 2020). "Data presented here showed that either ASXL1-R693X or RUNX1-R135T mutant alone did not have much effect on leukemia cells; however, cooperative mutations led to the enhancement of HIF-1α recruitments to the promoter region of the ID1 gene." (PMID 31640815, 2019). "Our results of reduction of ID1 expression by the inhibition of HIF-1α in transformed leukemia cells supports that ID1 is controlled by HIF-1α, which might be deregulated by either ASXL1 or RUNX1 mutation or coexisted mutant of both genes." (PMID 31640815, 2019). "RUNX1 mutant directly enhanced the transcriptional activity of HIF-1α and increased its target gene expression such as ID1 which could be a potential target for future therapy in ASXL1-mutated leukemia." (PMID 31640815, 2019).
leukemia (continued). "To further determine the functional significance of this glycolytic phenotype and the HIF1α pathway in MLL-r leukemia cell line resistance to CCI-006, we investigated the effect of HIF1A gene silencing on the responsiveness of the resistant MLL-r RS4;11 cell line to CCI-006." (PMID 30670779, 2019). "Moreover, IM treatment increases HIF-1α activation through MAPK pathway in leukemia progenitor cells." (PMID 31870110, 2019). "In comparison to the sensitive cells, the unresponsive MLL-rearranged leukemia cells were characterized by a more glycolytic metabolic phenotype, exemplified by a more pronounced sensitivity to glycolysis inhibitors and elevated HIF1α expression." (PMID 30670779, 2019). "Although several strategies are being explored in solid tumors at the moment, including the use of novel antisense oligonucleotides against HIF1α and small-molecule HIF1α inhibitors, the potential therapeutic application of HIF1α inhibition for leukemia remains to be determined." (PMID 30781787, 2019). "Chidamide-mediated p300 over-acetylation and the subsequent HIF1α pathway suppression may provide a new sight for anti-leukemia drug development." (PMID 29212263, 2017). "Our data suggest that in acute monocytic leukemia an active HIF-1α-dependent pro-invasive pathway mediates the ability of leukemic cells to migrate and invade extramedullary sites and may be targeted to reduce leukemia dissemination." (PMID 27447550, 2016). "In acute myeloid leukemia (AML), in particular, controversial new findings indicate that HIF-1α can act either as an oncogene or a tumor suppressor gene, and this may depend on the stage of leukemia development and/or the AML sub-type." (PMID 27447550, 2016). "This study however did not address the role of HIF-1α in established human leukemia carrying the same oncogenic mutations." (PMID 27447550, 2016). "In addition however, acute silencing of HIF-1α led to prolonged inhibition of bone marrow colonization, as measured by in vivo luciferase activity at day 5 and day 9 from leukemia challenge, and prolonged mice survival." (PMID 27447550, 2016). "Thus, the in vivo HIF-1α deletion decreases the ability of tumor spread mediated by CSCs in leukemia." (PMID 24932611, 2014). "Finally, as it was recently reported that HIF-1α regulates maintenance of LICs, we analyzed the effect of HIF-1α inhibition on leukemia self-renewal in vitro." (PMID 24711541, 2014). "HIF-1α and VEGF are considered as potential targets for cancer therapy because they play an important role in the progression of many types of cancer, including leukemia, and are associated with resistance to therapy and poor prognosis." (PMID 23626851, 2013). "Indeed, knockdown of Hif1α in LSC or in bone marrow stromal cells diminished leukemia growth in vivo." (PMID 24223100, 2013). "Many known HIF-1α targets could mediate the protection conferred by hypoxia, and a number of those have been validated as chemoresistance factors in leukemias (i.e., MDR-1, Nur-77, CXCR4 and others)." (PMID 21853076, 2011). "Which HIF-1α targets mediate hypoxia-induced chemoprotection in leukemia cells and whether there is any contribution from HIF-2α requires further investigation." (PMID 21853076, 2011). "Given the phenomena we observed, Selinexor, the inhibitor of CRM1, was administered, and it proved that it could effectively cause the accumulation of PHD2 in the nucleus and decrease the protein levels of PHD2 and HIF-1α in the leukemia cells under hypoxic conditions." (PMID 41394810, 2025). "In addition, treatment with vitamin C could promote the degradation of HIF-1α by stimulating HIF prolyl hydroxylases, and growth-inhibitory effect of vitamin C in leukemia cell cultures correlated with the downregulation of HIF-1α expression." (PMID 36979633, 2023).
leukemia (continued). "Similarly, low oxygen levels lowered T-ALL cell sensitivity to chemotherapy and preserved their ability to initiate leukemia progression in vivo, while silencing of HIF1α sensitized leukemic cells to treatment, thus pointing to HIF1α as an important regulator of T-ALL chemoresistance." (PMID 36059690, 2022). "Hsp90β inhibition could kill leukemia cells by promoting the degradation of the Hsp90 client HIF1α." (PMID 36139005, 2022). "Of note, in the AML1-ETO mouse model it was reported that genetic deletion of the HIF1α gene resulted in compensatory expression of HIF2α, which led the authors to suggest that HIF2α upregulation may lead to increased leukemia aggressiveness, at least in some genetic backgrounds of AML." (PMID 36059690, 2022). "Furthermore, we found strong activation of Hif1α, Stat1 and Stat4 pathways in Gr-1+ population upon DS-5272 treatment, indicating the enhanced inflammatory signaling in the relatively differentiated leukemia cells in agreement with the RNA-seq data above." (PMID 31653912, 2019). "Therefore, it is conceivable that MLL-r leukemia cells with lower expression of the MEIS1/HIF1α pathway are less metabolically flexible in their response to specific mitochondrial stress induced by CCI-006, and thus sensitive to the inhibition of mitochondrial respiration induced by the compound." (PMID 30670779, 2019). "Interestingly, upregulation of Hif1α was most evident in differentiated Gr-1+ leukemia cells." (PMID 31653912, 2019). "In this context, we demonstrated that HIF-1α regulates the clonogenicity of leukemic cells, as a read-out of leukemia-initiating capacity, but also other pro-leukemogenic functions such as bone marrow neo-angiogenesis, chemotaxis and leukemia migration/dissemination." (PMID 27447550, 2016). "Taken together, these results indicate that in AML-M5 HIF-1α plays specific pro-oncogenic functions that are mainly related to promoting leukemia cell motility and dissemination, but robust HIF-1α suppression may exert anti-leukemic functions also by inducing cell death and blasts eradication." (PMID 27447550, 2016). "Furthermore, it may be of interest to investigate whether the leukemia fusion protein AML1-MTG16 retains the MTG16 ability for degradation of HIF1α." (PMID 25974097, 2015). "However, a specific functional interaction of HIF-1α with oncogenic fusion proteins causative of specific leukemia sub-types has not yet been investigated." (PMID 24711541, 2014). "Overexpression of HIF-1α confers doxorubicin resistance in AML cells and synergizes with leukemia-derived macrophage migration inhibitory factor (MIF) to enhance cellular proliferation and survival." (PMID 40791591, 2025). "It is worth noting that ASH1L also co-localized with HIF-1α on the promoter regions of genes in leukemia cells; however, only 32.5% (1132 in 3482) of ASH1L target genes were shared with HIF-1α, which are distinct from those in metastatic PCa." (PMID 40394007, 2025). "Downregulation of HIF1α, oxidative phosphorylation, and PI3kinase pathways at EOI along with the regulators IFNG, TNF, VEGFA, IL1B in B cells is likely to impede leukemia supportive pro-inflammatory signaling." (PMID 37532715, 2023). "Previous studies reported that YBX1 affected mRNA translation of HIF1α and MYC to promote sarcoma metastasis and leukemia progression at a posttranscriptional level." (PMID 37161388, 2023).
leukemia (continued). "To validate and compare the functional consequences of HIF1α and HIF2α suppression in vivo, we utilized two AML patient‐derived xenograft (PDX) models from leukemia samples collected at diagnosis." (PMID 37807875, 2023). "This difference is mainly found in proteins functionally related to each pathology, for example: sCD44, HIF1A, ZMYM3 or PTPRC for CSF + LM in lymphoma and S100A9, TRAF3, KLK3, KLK2, PTPRC, among others, in the case of CSF + LM in leukemia." (PMID 35053611, 2022). "Suppression of the mitochondrial ROS/HIF-1α pathways through direct inhibition of HIF-1α induced ETC complex I dysfunction and metabolic pathways in leukemia and lymphoma." (PMID 35986432, 2022). "To corroborate the impact of HIF-1α inhibition of YY1 positive expression, we cultured RS4;11 leukemia cells in hypoxic conditions over time." (PMID 35163649, 2022). "Based on independent findings regarding the expression of HIF-1α and YY1 in lymphomas and leukemia, we proposed that there is a correlation between these proteins." (PMID 35163649, 2022). "In a patient-derived xenograft model (with knockdown of MIF, HIF-1α, and HIF-2α), leukemia cell proliferation was promoted by hypoxia and HIF-1α." (PMID 34066861, 2021). "In another study, it was indicated that TLR7 ligands (e.g., resiquimod—an analog of Imiquimod) induced HIF1A accumulation in a time- and concentration-dependent manner in THP-1 human leukemia monocytic macrophages." (PMID 34681079, 2021). "Numerous studies have established the oncogenic roles of VHL/HIF-1α and SOCS/JAK-STAT pathways in regulating leukemia cell growth and hematological malignancies." (PMID 32683582, 2021). "The transcription factor HIF-1α is overexpressed in chronic lymphocytic leukaemia (CLL), where it promotes leukaemia progression by favouring the interaction of leukaemic cells with protective tissue microenvironments." (PMID 32397871, 2020). "We showed that the group of sensitive MLL-r leukemia cells is characterized by a particular gene expression profile (low HOXA9, MEIS1, and CMYC mRNA levels) and low levels of MEIS1/HIF1α protein expression." (PMID 30670779, 2019). "The activated Hif1α-PD-L1 pathway appears to counteract the NK cell-mediated cytotoxicity, thereby contributes to therapeutic resistance in MLL-AF9 leukemia." (PMID 31653912, 2019). "Together, we conclude that both HIF1–α and HIF2–α contribute to the hypoxic induction of ARG2 in leukemia cells." (PMID 30307989, 2018). "Taken together these data show that hampering HIF-1α expression in a mouse model of AML-M5 results in impairment of bone marrow homing, colonization and leukemia progression, thus indicating that in this AML context HIF-1α plays oncogenic functions." (PMID 27447550, 2016). "In accordance with these data, inhibition of HIF-1α in a number of AML-M5 cell lines impairs leukemia motility and delays leukemia propagation in vivo." (PMID 27447550, 2016). "In AML in particular, a number of studies with human cells and xenograft mouse models have recently suggested that HIF-1α and HIF-2α play pro-leukemogenic functions by regulating leukemia progression and maintenance of leukemia initiating cells (LICs)." (PMID 27447550, 2016). "In the leukemia mouse model, we did observe increased gene expression of VEGF, HIF-1α and ANGPT-2, which were significantly reduced after HF treatment." (PMID 26099922, 2015). "It was recently shown that the HIF-1α gene is expressed in the stem cell compartment of mouse lymphoma and human AML, and that it plays a crucial role in promoting the maintenance of leukemia stem cells in AML and chronic myeloid leukemia." (PMID 25452766, 2014). "We found that although acting predominantly as a transcriptional repressor, PML-RARα functionally cooperates with HIF-1α and activates the expression of a number of HIF-target genes, which then regulate leukemia progression at multiple levels." (PMID 24711541, 2014).